LTN1 (listerin E3 ubiquitin protein ligase 1)
Description:
E3 ubiquitin-protein ligase component of the ribosome quality control complex (RQC), a ribosome-associated complex that mediates ubiquitination and extraction of incompletely synthesized nascent chains for proteasomal degradation. Within the RQC complex, LTN1 is recruited to stalled 60S ribosomal subunits by NEMF and mediates ubiquitination of stalled nascent chains. Ubiquitination leads to VCP/p97 recruitment for extraction and degradation of the incomplete translation product (By similarity).
Synonyms: C21orf10; C21orf98; KIAA0714; RNF160; ZNF294; FLJ11053; LISTERIN
Tractability: PROTAC: UniProt records ubiquitination sites on it; ubiquitination databases record sites on it; its protein half-life has been measured.
Target class: Enzyme; Transferase
Gene: Protein-coding gene on chromosome 21 (28,928,144 to 28,992,956, reverse strand). Ensembl gene ENSG00000198862.
Subcellular location: Cytoplasm, cytosol
Subcellular location (Human Protein Atlas): Cytosol
Pathways (Reactome):
Immune System: Antigen processing: Ubiquitination & Proteasome degradation
Metabolism of proteins: Ribosome Quality Control (RQC) complex extracts and degrades nascent peptide
Gene Ontology:
Molecular function: protein binding; ubiquitin protein ligase activity; ribosomal large subunit binding; ubiquitin-protein transferase activity; zinc ion binding
Biological process: rescue of stalled ribosome; ribosome-associated ubiquitin-dependent protein catabolic process; protein autoubiquitination; protein ubiquitination
Cellular component: cytosol; cytosolic ribosome; RQC complex
Genetic constraint (gnomAD): Loss-of-function variants: 45 observed, 122.6 expected, observed/expected ratio (o/e) 0.37, 90% interval 0.29 to 0.47. The upper end of that interval is the gene's LOEUF score, 0.47, which puts it in group 2 of 6, group 1 being the genes least tolerant of losing a copy. Missense variants: 1,253 observed, 1,528.5 expected, observed/expected ratio (o/e) 0.82, 90% interval 0.78 to 0.86. Synonymous variants: 470 observed, 550.78 expected, observed/expected ratio (o/e) 0.85, 90% interval 0.79 to 0.92.
Homologues: Orthologues: chimpanzee LTN1 (99% identical), macaque LTN1 (97% identical), dog LTN1 (91% identical), rabbit LTN1 (91% identical), pig LTN1 (90% identical), guinea pig LTN1 (87% identical), rat Ltn1 (87% identical), mouse Ltn1 (85% identical), tropical clawed frog ltn1 (62% identical), zebrafish ltn1 (52% identical), Drosophila melanogaster Ltn1 (26% identical), Caenorhabditis elegans Y54E10A.11 (19% identical).
Diseases named in the same sentence as LTN1 in open-access papers:
LTN1 is named in the same sentence as 16 diseases in open-access papers, as found by Europe PMC text mining. Sharing a sentence is not in itself a finding about the gene and the disease. The quoted sentences say what the papers report.
cognitive disorder (2 papers, 2023 to 2025). A disease affects cognitive processes. "Together, these results indicate that Ltn1 KO mice showed behavioral abnormalities associated with cognitive disorders and a cohort of the behavioral deficits is caused by the aberrantly increased TTC3 protein due to the loss of LTN1." (PMID 36917672, 2023). "Instead, however, we found that the aberrantly accumulated TTC3 protein elicits defects of neurite outgrowth and underlie cognitive disorders in Ltn1 KO mice." (PMID 36917672, 2023). "Ltn1 KO mice showed behavioral deficits associated with cognitive disorders, a subset of which were restored by TTC3 knockdown in medial prefrontal cortex." (PMID 36917672, 2023). "Remarkably, however, we found that abnormally increased TTC3 protein induced various deleterious effects on neuronal functions; the overaccumulated TTC3 protein in Ltn1 KO neurons and mice results in dendritic and synaptic abnormalities and behavioral deficits associated with cognitive disorders." (PMID 36917672, 2023). "The enhanced protein level of TTC3 reduced not only dendritic outgrowth but also surface-localized GABAAβ3 receptor levels, which would at least partly account for the abnormal behaviors associated with cognitive disorders in Ltn1 KO mice, as suggested previously." (PMID 36917672, 2023). "Consistently, Ltn1‐deficient mice showed accumulation of TTC3, resulting in dendritic and synaptic abnormalities, along with behavioural deficits associated with cognitive disorders." (PMID 38949989, 2025). "Together, these results support our observation that Ltn1 KO mice show behavioral deficits associated with cognitive disorders rather than severe neurodegenerative disorders." (PMID 36917672, 2023). "Instead, Ltn1 KO mice showed phenotypes associated with cognitive disorders without showing obvious deficits in locomotor activity, neuromuscular function, and neuronal loss at 4 to 5 mo of age." (PMID 36917672, 2023).
ovarian carcinoma (2 papers, 2021 to 2024). A malignant neoplasm originating from the surface ovarian epithelium. "These proteins include LTN1 (ovarian cancer), GBE1, CACNA1E and ADCY10 (lung cancers), as well as PLEKHS1 and ADNP (bladder cancer)." (PMID 38951817, 2024). "Eight immune factors (IFT57, MAL, ANXA4, SCRN1, LTBR, KIFAP3, HSPA5, and LTN1) were positively correlated with poor prognosis of ovarian cancer, whereas six immune factors (PSMB9, FOXJ1, CTSH, MIF, CTSD, and PSMB8) were negatively correlated with poor prognosis of ovarian cancer." (PMID 34109184, 2021).
amyotrophic lateral sclerosis (1 paper, 2020). Amyotrophic lateral sclerosis (ALS) is a neurodegenerative disease characterized by progressive muscular paralysis reflecting degeneration of motor neurons in the primary motor cortex, corticospinal tracts, brainstem and spinal cord. "In mice, a hypomorphic LTN1 allele induces a progressive neurodegeneration that shares phenotypic similarities with amyotrophic lateral sclerosis (ALS)." (PMID 31945107, 2020).
Anxiety (1 paper, 2023). Intense feelings of nervousness, tension, or panic often arise in response to interpersonal stresses. "We next tested Ltn1 KO mice for anxiety-like behaviors, first with the elevated plus maze (EPM) test." (PMID 36917672, 2023). "Importantly, the decreased anxiety phenotype manifested by the marble-burying test and the defects in nest building capability in Ltn1 KO mice were fully restored by the KD of TTC3." (PMID 36917672, 2023). "Ltn1 KO mice spent more time on the open arms, suggesting reduced anxiety." (PMID 36917672, 2023).
autism spectrum disorder (1 paper, 2023). A spectrum of developmental disorders that includes autism, and Asperger syndrome. "In the prepulse inhibition (PPI) test, Ltn1 KO mice showed significantly reduced PPI, which is a typical phenotype observed in both autism spectrum disorder (ASD) and schizophrenia." (PMID 36917672, 2023).
Parkinson disease (1 paper, 2020). A progressive degenerative disorder of the central nervous system characterized by loss of dopamine producing neurons in the substantia nigra and the presence of Lewy bodies in the substantia nigra and locus coeruleus. "It is possible that degenerating neurons in these LTN1-hypomorphic mice harbor toxic CAT tail aggregates, as has been observed in a Drosophila model of Parkinson Disease." (PMID 31945107, 2020).
Sensorimotor neuropathy (1 paper, 2020). "Thus, the more severe R86S allele may also cause a sensorimotor neuropathy, similar to Ltn1 mutant mice." (PMID 32934225, 2020).
tumours (2 papers, 2017 to 2021). "The most recurrent frameshift MSI events are found in ACVR2A (51.6% of the tumours), KIAA2018 (51%), SLC22A9 (50%), ASTE1 (45%), TGFBR2 (44%), NDUFC2 (36%), LTN1 (36%) and SEC31A (36%)." (PMID 28585546, 2017).
LTN1 also shares sentences with these, for which no sentence is quoted: Alzheimer disease (1 paper); behavioral disorders (1); bladder cancer (1); Down syndrome (1); hepatocellular carcinoma (1); lung carcinoma (1); schizophrenia (1); virus infection (1).